MMP1 (matrix metallopeptidase 1)
Diseases named in the same sentence as MMP1 in open-access papers (continued):
Sharing a sentence is not in itself a finding about the gene and the disease.
tumor (continued). "The total RNA was isolated from additional tumor samples and intact skin, DNase digested, and subjected to MMP1 RT-qPCR, with RPS13 serving as the reference housekeeping gene." (PMID 38891088, 2024). "Consistent with previous findings in mouse models, the knockdown of SPHK1/MMP1 significantly reduced tumor growth, increased intratumoral PD-L1+ cell density, and inhibited CD8+ T cell exhaustion." (PMID 39629135, 2024). "Collagens type I and III are key components of the extracellular matrix, and MMP-1 plays an important role in their degradation, thus participating in tumor progression." (PMID 39769318, 2024). "As dominant components of the tumor stroma, fibroblasts constitute an important source of Matrix metalloproteinase (MMPs) including mainly MMP1." (PMID 38320998, 2024). "As such, several studies have already found a significant association between MMP-1, MMP-2, MMP-9, and MMP-13 expression and tumor development, as well as aggressiveness and fast metastatic pattern." (PMID 39063046, 2024). "RT-qPCR revealed an almost 26-fold upregulation of MMP1 transcription in tumor tissue compared to intact skin." (PMID 38891088, 2024). "As expected, MMP1-downregulate fibroblasts lost the function for promoting tumor cell invasion compared to SiNC group." (PMID 38320998, 2024). "Another important mediator of tumor cell detachment is MMP-1, which degrades the ECM molecules that hold together the cells constituting the neoplastic mass." (PMID 39120324, 2024). "The IF staining of primary tumor cells explanted from the tumors for MMP1 showed that the metalloproteinase is uniformly expressed in the cytoplasm of 100% of tumor cells." (PMID 38891088, 2024). "In the current study, we elucidated the molecular mechanism by which SPHK1 regulates tumor PD-L1 expression via MMP1." (PMID 39629135, 2024). "In the case of horses DIM and LOR, tumor tissue and intact skin were available for the comparison of MMP1 transcription within each individual." (PMID 38891088, 2024). "High levels of tumour-derived Mmp1, observed in most D. melanogaster cachexia models, lead to fat body and muscle degeneration." (PMID 39682725, 2024). "The six-BMRGs risk score, comprising CD151, CTSA, MMP1, ROBO3, ADAMTS5 and MEP1A, was established for the prediction of clinical prognosis, tumor microenvironment characteristics, and immunotherapy response in HCC." (PMID 39070142, 2024). "MMP-1, 8 and 13 also known as collagenase 1, 2 and 3 have a pro-tumorigenic role by cleaving fibrillar collagens and enhancing tumor cell motility." (PMID 38659022, 2024). "The pronounced upregulation of the MMP1 transcription according to RNAseq was further confirmed by MMP1 RT-qPCR from additional tumor and skin samples." (PMID 38891088, 2024). "The prospect of SPHK1/MMP1 knockdown combined with the anti-PD-1 therapeutic regimen represents an efficacious approach to enhance T cell-mediated anti-tumor immunity, offering a promising avenue for potential advancements in cancer therapy." (PMID 39629135, 2024). "The aim of this study was to evaluate the role of SPHK1 in anti-tumor immunity, reveal the novel molecular mechanism of PD-L1 regulation through MMP1, and further explore the clinical significance of the SPHK1-MMP1 axis in HNSCC immunotherapy." (PMID 39629135, 2024). "Immunofluorescent staining for MMP1 and myofibroblasts marker α-smooth muscle actin (ACTA2) revealed that the immuno-colocalization of MMP1 (red) and ACTA2 (green) was detected in stroma and MMP1 protein was highly expressed around the tumor cells." (PMID 38320998, 2024). "A central role Twist1 plays is to suppress the expression of E-cadherin and to promote the expression of mesenchymal-associated proteins including PDGFR-β, MMP-1, and BMI1 in tumor cells, leading to tumor progression and metastasis." (PMID 38416830, 2024). "Conversely, the U87MG-AGBL4-KD2+MMP1-OE group showed accelerated tumor progression relative to the U87MG-AGBL4-KD group." (PMID 39007144, 2024).
tumor (continued). "As collagen types I and III represent an essential part of the extracellular matrix, collagenases such as MMP-1 express a major role in its degradation and are also essential for tumor progression." (PMID 39063046, 2024). "Previously, substantial expression of MMP-1 and MMP-3 was observed in OSCC cases involving poor prognosis and metastasis, and this is associated with tumor progression and poor survival rates." (PMID 36839884, 2023). "In the process of effective PAR1CAR-T therapy, targeted tumor cells and CAFs were eliminated, and simultaneously, the MMP1-enriched ECM was degraded, which therefore led to loss of MMP1." (PMID 37667257, 2023). "MMP-10 is expressed by tumor cells in cSCC and it has been shown to contribute to cSCC progression by activating latent MMP-1 and MMP-13." (PMID 37864034, 2023). "Conversely, MMPs such as MMP1 secreted from tumor cells promote the transdifferentiation of fibroblasts into CAFs." (PMID 36816030, 2023). "Tumor sections from control mice groups had much-higher Ki67 and MMP1 levels than those sections from genetically modified T-cell-treated mice (*** p < 0.001)." (PMID 37667257, 2023). "Because of its role in extracellular matrix degradation in tumor invasion, dysregulation of MMP1 transcription promotes tumor metastasis." (PMID 36817446, 2023). "We further explored the prognostic value of PRKRA and MMP1 in PC and found that PRKRA and MMP1 were overexpressed in tumor tissues and correlated with poor prognosis." (PMID 37484321, 2023). "This suggests that the ALF-conditioned media induced the SCLC cells to secrete more GRO-α, IL-8, and MMP-1 and these factors all play key roles in angiogenesis and tumor metastasis." (PMID 37608896, 2023). "The results demonstrated that the abundance of DOHH, P4HA3 and MMP1 were higher in tumor cases than normal cases." (PMID 37957566, 2023). "In the present study, PCDH10 overexpression significantly decreased the expression of genes associated with tumor progression and metastasis, including EREG, MMP1, MMP9, TGFB1, RASA4, and CXCL8, in GC cells." (PMID 37147733, 2023). "Overexpression of MMP1 and MMP9 in solid tumors was associated with tumor invasion and metastasis have been reported." (PMID 37052818, 2023). "Previous studies mainly focused on the role of MMP1 in tumor invasion and metastasis, because of its ability of extracellular matrix degradation." (PMID 37484321, 2023). "It has been established that PAR1 expression is increased in tumor cells, and this is accompanied by an increase in the activity of matrix metalloproteinase-1 (MMP1), which functions as a PAR1 agonist." (PMID 37047169, 2023). "Further, it can be seen that the expression of MMP1 was related to the age and tumor stage of GC patients, that is, the MMP1 expression significantly increased in the cohorts at age > 60 and Stage II-IV (p < 0.05)." (PMID 37957566, 2023). "ROS can also induce tumor cells to secrete matrix metalloproteinases such as MMP-1, which promote vascular structure formation in the tumor microenvironment." (PMID 37033606, 2023). "In our study, we found several MMP molecules to be significantly overexpressed in metastatic cell lines compared to primary tumor cells (e.g., MMP1, MMP2, MMP3, MMP9), with a dramatic increase registered for MMP2." (PMID 37047539, 2023). "We also detected tumor cell proliferation by Ki67 and MMP1 (a PAR1 ligand, also known as collagenase 1)." (PMID 37667257, 2023). "MMPs can be divided six subfamilies, of which MMP1 and MMP13 are collagenases and MMP3 and MMP10 are stromelysins, which have long been associated with tumor invasion, metastasis and angiogenesis." (PMID 36824434, 2023). "ROS-induced secretion of MMP-1 from tumour cells promoted vessel growth within the tumour microenvironment." (PMID 36701089, 2023).
tumor (continued). "Our analysis demonstrated that MYLK2, FAM83D, STC2, CCDC112, EPHX4 and MMP1 were differentially expressed between tumor and normal tissues, with higher expression in tumor tissues than in normal tissues (p < 0.0001)." (PMID 37309005, 2023). "IGF2BP3 is an RBP and can affect tumor progression by targeting mRNA for MMP1, CD44, CDK164, ABCG2, IGF2 and other genes." (PMID 37340423, 2023). "lgl tumours express MMP1 themselves, whereas brat tumours rely on increased Mmp1 expression in the ovaries for metastasis." (PMID 36899813, 2023). "It has previously been shown that senescent fibroblasts promote early tumor growth by secreting MMP1 (interstitial collagenase) and MMP2 (72kDa type IV collagenase), which modulate PAR1 in malignant cells via a paracrine manner." (PMID 37046588, 2023). "Comparison of each factor before and after SCLC cell regrowth revealed that GRO-α, IL-8 and MMP-1 had significantly higher expression in the media with SCLC cell recurrence than in the original tumor before chemotherapy." (PMID 37608896, 2023). "They found that the matrix metalloproteinase MMP1 was required for colonisation of the ovarioles in both tumours, but the source of MMP1 was different." (PMID 36899813, 2023). "Eventually, we found a significant correlation between MMP1 expression and stromal score in 24 tumor types, and all of them were positively correlated." (PMID 36727076, 2022). "The MMP-1 detectability was at a picogram level; thus, the fabricated chemosensor is suitable for MMP-1 determination in real samples of cancerous tumor human cells, as was demonstrated using A549 cells in tissue culture." (PMID 36421137, 2022). "The PI3K/AKT pathway was activated when MMP1 was expressed ectopically in tumor cells, resulting in tumor development and metastasis." (PMID 36081670, 2022). "Consistent with the result of WB, higher expression of MMP1 in tumor than normal tissues (P < 0.001) were corroborated by qPCR." (PMID 35948625, 2022). "MMP-1/protease-activated receptor-1 (PAR1) signaling axis plays an essential role in tumor angiogenesis by inducing vascular permeability." (PMID 35545767, 2022). "Our findings revealed that MMP1 expression was higher in 22 tumor types and only lower in KICH than in paired normal tissues." (PMID 36727076, 2022). "First, MMP1 expression was examined in the tumor tissues obtained after xenografting MCF-7 and MCF-7/tamR cells into nude mice, as described in our previous study." (PMID 35267540, 2022). "Firstly, we confirmed that dsRNAs against Mmp1 and Mmp2 efficiently depleted the relevant mRNAs in the LG tumor cells." (PMID 36226812, 2022). "Colony formation assays were also performed to analyze the cell viability of tumor cells under triolein treatment and MMP1 knockdown, where we observed that triolein and MMP1 knockdown both inhibited cell proliferation of all the TC cell lines." (PMID 36479070, 2022). "Matrix metalloproteinase-1 (MMP-1) is an interstitial collagenase that degrades collagen types I, II, and III; its overexpression is implicated in the invasive growth of tumor cells." (PMID 36421137, 2022). "Our study comprehensively proved that MMP1 expression is related to clinical prognosis and tumor immune infiltration, and MMP1 can become a prognostic and immunological biomarker." (PMID 36727076, 2022). "The induction of MMP-1 and MMP-2 has been associated with HG-CD147, which promotes tumor invasion and migration." (PMID 35805895, 2022). "Subsequently, the involvement of MMP1 in tumor growth and tam resistance was investigated in the xenografted mice." (PMID 35267540, 2022). "Matrix metalloproteinase-1 (MMP-1) is the principal LCC-secreted factor that enhances the tumor-promoting traits." (PMID 36119505, 2022). "Consistently, bioinformatic analysis revealed that the expression level of MMP1 was correlated with advanced tumor stage and poor prognosis." (PMID 35414794, 2022).
tumor (continued). "In both cell culture and mouse models of large cell lung carcinoma cell lines (LCC), the overexpression of mmp1 has been described to be necessary for the induction of fibroblast senescence and consequent tumor promotion." (PMID 35805895, 2022). "Tumor-bearing status (HR = 1.819, 95%CI = 1.137–2.911, P = 0.013) and MMP1 expression (HR = 1.236, 95%CI = 1.037–1.473, P = 0.018) were independent factors impacting the OS of patients with LIHC." (PMID 35948625, 2022). "MMP1 is composed of tumor cells and stromal cells, and it is well known that the over-expression of MMP1 promotes the migration and invasion of HCC cells." (PMID 35699863, 2022). "IHC also determined that the expression of HPRT1 and MMP1 were consistent in the tumor tissues of nude mice." (PMID 35205603, 2022). "High expression of MMP1 was associated with poor overall survival (OS) and disease-free survival (DFS) in some tumor types." (PMID 36727076, 2022). "Increased Mmp1 expression has also been observed in RasV12 scrib−/− and RasV12 Csk−/− larval tumor models, as well as in the adult ykiact tumor model." (PMID 35319749, 2022). "Although the function of TIICs in carcinogenesis is still controversial, a cluster of studies have reported that MMP1 alongside TIICs plays a vital role in tumor progression." (PMID 35948625, 2022). "Comparing its expression in PTC and ATC tumor cells, we found that MMP1 showed major expression in ATC tumor cells but lower expression in PTC tumor cells." (PMID 36479070, 2022). "Based on GEO database, it was further verified that MMP1 expression was higher in tumor tissues than normal tissues in GSE14520 (P < 0.001) and GSE 25,097 (P < 0.05)." (PMID 35948625, 2022). "We investigated expression levels of CTGF and MMP-1 genes in paraffin-embedded tumours and adjacent normal tissue blocks (ADJ) by Real Time-PCR." (PMID 35456495, 2022). "It was shown that an increase in MMP-3 expression in tumor cells positively correlated with an increased expression of MMP-1." (PMID 36231910, 2022). "In the invasive tumor group we found two significant positive correlations: first between MMP-1 and MMP-2 expression (rho = 0.306, p = 0.031) and second between TIMP-2 and MMP-9 expression (rho = 0.464, p = 0.001)." (PMID 36551933, 2022). "The interrelation of MMPs with the tumor microenvironment is complex, as some of them (MMP-1, MMP-9) are also induced by external carcinogens such as tobacco or betel quid chewing." (PMID 36547091, 2022). "In malignant tumors, proliferation of tumor cells is usually accompanied by high expression of MMP1 and MMP1 is activated to degrade the extracellular matrix and attenuate hindrance during cell movement, which in turn promotes tumor invasion and metastasis." (PMID 36727076, 2022). "The COX2 produced by tumor cells can induce the production of prostaglandins, which promote high expression of MMP-1 in tumor cells and degrade claudin and ZO-1 on the BBB." (PMID 36338717, 2022). "The experiments in vitro and in vivo demonstrated that knockdown of MMP1 attenuated tumor growth and migration." (PMID 35426219, 2022). "The mRNA expression level of MMP-1 was significantly higher in tumour tissues compared with adjacent normal tissues (p < 0.0253)." (PMID 35456495, 2022). "It is involved in tumor invasion and progression and can activate other MMPs, such as MMP-1, MMP-7, MMP-8, MMP-9 and MMP-13, which have an established role in OSCC." (PMID 36547091, 2022). "While some studies have reported a relationship between MMP1 and HCC, its specific role in prognosis and the associated tumor-immunity are still unclear." (PMID 35948625, 2022). "For discrimination of the normal and tumour sampling zones, we were able to derive an effective gene-based classifying model for molecular abnormality based on a panel of eight genes (MMP1, MMP12, MYO1B, TNFRSF12A, WDR66, LAMC2, SLC16A1 and PLAU)." (PMID 35327656, 2022).
tumor (continued). "The potential mechanism of MMP1 and tumor immune microenvironment and relevant immunotherapy cohort can be the focus of future research." (PMID 35948625, 2022). "In comparison with the results obtained by other authors, it was demonstrated that an increase in the expression of MMP-3 in tumor cells positively correlated with the increased expression of MMP-1." (PMID 36231910, 2022). "In summary, the present study showed that metabolic reprogramming towards PPP promotes metastasis and proliferation of acidosis-adapted PDAC cells via AMPK/YAP/MMP1 axis, enriching the mechanism by which acidic environment promotes tumor progression." (PMID 35414794, 2022). "They discovered that PM2.5 effectively induces proliferation in H1292 tumor cells in vitro via a mechanism involving cytokines, matrix metalloprotease 1 (MMP1), and IL-1ß." (PMID 35742761, 2022). "This research also showed that MMP1 had the highest mutation frequency in CESC, and the mutation frequency in HNSC was third in all tumor types, which was agreed with earlier studies reporting that genetic alterations in MMP1 were associated with HNSC." (PMID 36727076, 2022). "Downregulation of MMP1 using shRNA inhibited the growth of the MCF-7/tamR cells in vitro as well as that of the tumor tissues derived from the MCF-7/tamR cells in the animal model." (PMID 35267540, 2022). "Overall, our data show that TIMP‐1 in hASCs plays a major role in the expression of ECM proteins in tumor spheroids by regulating MMP‐1 activity." (PMID 35600659, 2022). "Based on univariate logistic regression, Age > 60 (P = 0.038), tumor-bearing status (P = 0.002), albumin < 3.5 (P = 0.004), Child–Pugh B (P < 0.001) and MMP1 (P < 0.001) were significantly correlated with OS." (PMID 35948625, 2022). "We found that CAFs was positively related to MMP1 expression in 31 tumor types, and CAFs was significantly related to MMP1 expression in 18 tumor types." (PMID 36727076, 2022). "The MMP1 expression level in the tumor tissues of LIHC was much higher than the adjacent normal tissues (P < 0.001)." (PMID 35948625, 2022). "TIMER2 was utilized to investigate MMP1 expression levels between tumor tissues and control tissues from the TCGA database." (PMID 36727076, 2022). "In order to investigate the expression level of MMP1 in tumor specimens of HNSCC patients, we preliminarily evaluated the mRNA expression level of MMP1 by interrogating the public gene expression database including TCGA and GEO." (PMID 36105241, 2022). "In situ immunohistochemistry of tumor sections validated the elevated MMP1 expression in MCF-7/tamR cells compared to that in parental MCF-7 cells." (PMID 35267540, 2022). "A newly discovered mechanism of MMP1 in tumor promotion is by activating PAR1 to cleave downstream oncogenic signaling pathways." (PMID 36225568, 2022). "Although MMP1 is involved in the tumor-immune-related progression of some carcinomas, there is barely any studies regarding the interaction between MMP1 and TIICs in HCC proliferation and migration." (PMID 35948625, 2022). "MMP1 is also involved in G protein signal transduction, regulating tumor angiogenesis, and promoting tumor cell resistance." (PMID 36727076, 2022). "In OSCC, MMP1 has previously been reported as overexpressed in tumours relative to normal tissue and proposed as a biomarker of disease recurrence." (PMID 35327656, 2022). "The gene expressions levels of CTGF and MMP-1 were significantly increased (p = 0.0002, p = 0.0356, respectively) in tumours with a high level of TGF-β protein." (PMID 35456495, 2022). "Our pan-cancer analysis comprehensively proved that MMP1 expression is related with clinical prognosis and tumor immune infiltration, and MMP1 can become a prognostic and immunological biomarker." (PMID 36727076, 2022). "MMP-1 appeared down-regulated in most of tumor specimens (8/9, 89%) when compared to normal skin samples, except in sample T3." (PMID 36713871, 2022).